PCAT1 (prostate cancer associated transcript 1)
Diseases named in the same sentence as PCAT1 in open-access papers (continued):
Sharing a sentence is not in itself a finding about the gene and the disease.
tumor (continued). "To better assess the effect of PCAT-1 in vivo, we tested the anti-tumor mechanism of PCAT inhibition in mouse model." (PMID 32754302, 2020). "In this study we characterize for the first time the role of lncRNA PCAT-1 in Kras-related lung chemoresistance and its role in tumor stroma remodeling via immunosuppressive miR-182/miR217 expression and fibroblast differentiation." (PMID 32754302, 2020). "The tumour suppressor functions of miR‐129 on cell growth and signalling pathway were reversed by PCAT‐1." (PMID 32048803, 2020). "Overall, these findings demonstrate the versatile roles of PCAT-1 in sustaining lung immunosuppressive neoplasia through tumor microenvironment remodeling and provide new opportunities for effective metastasis inhibition, especially in chemoresistant tumors." (PMID 32754302, 2020). "Findings reveal that expression of PCAT-1 was significantly upregulated in metastatic (Stage III–IV) tumor tissues compared with early stage neoplasia (I–II) tissues." (PMID 32754302, 2020). "In conclusion, our findings reveal for the first time the key role of lncRNA PCAT-1 in regulating Kras-related lung chemoresistance and its role in tumor stroma remodeling via immunosuppressive miR-182/miR217 expression." (PMID 32754302, 2020). "Findings provide evidence that PCAT-1 can regulate tumor cell fate and cell differentiation, by disrupting cell cycle sequence." (PMID 32754302, 2020). "In agreement with this, our results showed that exosomal PCAT-1 contained in CAFs triggers a CD133/SOX2-related stem cell phenotype which promotes tumor growth and guides lymph node metastasis in vivo." (PMID 32754302, 2020). "To further confirm the expression of exosomal PCAT-1 in tumor stroma, we isolated CAFs and NFs from LC tissues and adjacent normal tissues." (PMID 32754302, 2020). "Aberrant expression of PCAT-1 in the tumor microenvironment triggers fibroblast differentiation which negative regulates p27/CDK6 by inducing G0/G1 cell cycle arrest and AMPK augmentation, contributing to a tumor-favoring metabolic status." (PMID 32754302, 2020). "In this study, we investigate the role of lncRNA PCAT-1 in chemoresistant immunosuppression and its involvement in tumor stroma remodeling." (PMID 32754302, 2020). "Above results identified a crucial role of PCAT-1 in promoting tumor growth and drug resistance through MAPK signaling pathway in MM." (PMID 31777580, 2019). "We also observed that introduction of siRNA to PCAT-1 reduces HNSCC tumor growth in preclinical model." (PMID 30987615, 2019). "We also observed increased expression of PCAT-1 in archived HNSCC patient samples as compared to adjacent non-tumor tissues." (PMID 30987615, 2019). "We subsequently observed that knockdown of PCAT1 led to smaller tumours compared with the KYSE30 control cells." (PMID 31273188, 2019). "Overexpression of PCAT-1 was seen in tumor samples (n = 519) compared to non-tumor tissues (n = 44)." (PMID 30987615, 2019). "We then analysed the expression of PCAT1 in different stages of ESCC tissues from the TCGA database and found elevated levels of PCAT1 in advanced tumours, which is consistent with its increase in the serum of patients with advanced tumours." (PMID 31273188, 2019). "We observed up-regulation of PCAT-1 in HNSCC patient samples compared to adjacent non-tumor tissues." (PMID 30987615, 2019). "The tumour weight of the PCAT1-knockdown group was also much lighter than that of the control group." (PMID 31273188, 2019). "Conversely, knockdown of PCAT-1 slowed down the multiplication rate of MM cells, enhanced anti-tumor effects medicated by Bort." (PMID 31777580, 2019). "According to the analysis, PCAT1 had recognition sites for several potential miRNAs, including miR-326, which is a tumour suppressor in multiple human cancers." (PMID 31273188, 2019). "The curves of tumor growth and volume revealed that PCAT-1 overexpression significantly increased the speed and size of xenograft growth in mice." (PMID 31777580, 2019).
tumor (continued). "On the other hand, injection of KYSE450 cells with higher PCAT1 expression led to larger and heavier tumours compared with control cells." (PMID 31273188, 2019). "PCAT1 induces cell proliferation in vitro and functions as a transcriptional repressor by regulating a broad range of genes, including known tumor suppressor genes such as BRCA2." (PMID 29861844, 2018). "By comparing malignant and non‐malignant epithelial cells in PSC, malignant cells showed high expression of marker genes associated with epithelial–mesenchymal transition (EMT) and tumour metabolism regulation related genes, such as HMGA2, FN1, PDE10A, and PCAT1." (PMID 41469334, 2026). "Targeted inhibition of PCAT‐1 reduces tumor growth in a preclinical model." (PMID 40231344, 2025). "Previous studies have indicated that the lncRNA PCAT-1 may regulate the c-Myc signaling axis and impair the DNA damage response, contributing to tumor progression." (PMID 40468332, 2025). "Additionally, we assessed the utility of PCAT1 in predicting tumor progression and treatment efficacy." (PMID 39640681, 2024). "PCAT1 was reported to regulate tumor cell proliferation, apoptosis, invasion and metastasis." (PMID 39640681, 2024). "Indeed, expression of PCAT1 in clinical tumor samples was extensively elevated compared to that in paracencerous or benign tissues." (PMID 39640681, 2024). "In addition, PCAT-1 overexpression in MM leads to tumor cell survival by stimulating the JNK/MAPK pathways, prolonging MM cell survival." (PMID 37987364, 2023). "We first detected the expression of PCAT1 in the primary tumor cell lines HCT116 and SW480." (PMID 36093435, 2022). "However, further verification for tumour immune effects of intervention PCAT1 combined with radiotherapy was objectively restricted in vivo." (PMID 35415876, 2022). "Similarly, in animal experiments, knocking down PCAT1 inhibited tumor growth, reduced tumor volume and weight, and significantly enhanced the antitumor effect of radiation compared with the NC group." (PMID 35692795, 2022). "PCAT1 depletion led to significant retard in the growth of the NSCLC tumours." (PMID 35415876, 2022). "In addition, Ki67, SOX2 and N‐cadherin were significantly downregulated in the PCAT1‐depleted tumours, while cGAS, STING and E‐cadherin were upregulated." (PMID 35415876, 2022). "In addition, IHC staining also revealed that the malignancy of tumor cells was significantly suppressed in the PCAT1 KD group." (PMID 35402284, 2022). "Tumor volume and weight were further reduced after knockout PCAT-1." (PMID 33980216, 2021). "No gene fusions were associated with TL ratio, but the PCAT1:CASC21 gene fusion was significantly associated with tumour TL (two-sided Mann–Whitney U test; n = 139, Q = 2.07 × 10−4)." (PMID 34824250, 2021). "However, the relationship between exosomal lncRNA PCAT1 and tumor grade, stage, and recurrence of BCa has been controversial across different studies." (PMID 34692482, 2021). "Targeted inhibition of PCAT-1 regresses tumor growth in nude mice." (PMID 30987615, 2019). "We observed that targeted inhibition of PCAT-1 reduces tumor growth in the mice." (PMID 30987615, 2019). "In addition, statistical analysis also represented a moderate correlation between UBC1 expression and lymph node metastasis (P = 0.005), and higher PCAT‐1 level was correlated with higher tumour grade (P = 0.01)." (PMID 30467945, 2019). "However, the level of PCAT-1 transcript was significantly lower in tumoral tissues compared with total tumor and ANCT tissues (P=0.02)." (PMID 28989584, 2017). "The authors described an increased expression of PCAT-1 in 64% of CRC tissues from 108 cases compared with matched 81 adjacent non-tumour tissues and found that the PCAT-1 gene copy number variation explains only a few percent of the observed PCAT-1 overexpression." (PMID 23875687, 2013).
tumor (continued). "Significant African-ancestry-specific findings include an elevated tumour mutational burden, increased percentage of genome alteration, a greater number of predicted damaging mutations and a higher total of mutational signatures, and the driver genes NCOA2, STK19, DDX11L1, PCAT1 and SETBP1." (PMID 36045292, 2022). "Moreover, circulating PCAT1 may promote tumour proliferation or chemoresistance to paclitaxel via exosomes transmitted to close or distant cells." (PMID 31273188, 2019). "To explore the potential of targeting PCAT1 in NSCLC, we established NSCLC tumour xenografts with PCAT1 stably depleted cells." (PMID 35415876, 2022). "Inhibition of PCAT1/SOX2 enhanced IR‐induced cGAS/STING activation and anti‐tumour immune responses." (PMID 35415876, 2022). "PCAT-1 expression is remarkably increased in ESCC tissues, which is significantly related to tumor invasion." (PMID 35645836, 2022). "We have shown, for the first time, that PCAT-1 knockdown can inhibit proliferation and apoptosis in NSCLC H1299/GR cells treated with gefitinib and inhibit tumor formation in vivo." (PMID 33980216, 2021). "Our final panel consisted of seven up‐regulated DElncRNAs (CCAT1, CCAT2, H19, HOTAIR, HULC, MALAT1, PCAT1), which were also known as oncolncRNAs and three down‐regulated lncRNAs (MEG3, PTENP1, and TUSC7) as tumor suppressor lncRNAs (tslncRNAs)." (PMID 33094859, 2021). "Elevated expression of PCAT-1 negative regulates p27/CDK6 expression by inducing G0/G1 cell cycle arrest through AMPK augmentation, contributing to a tumor-promoting status." (PMID 32754302, 2020). "PCAT-1 knockdown impaired CAF-mediated stromal fibroblast activation, and tumor-related chemoresistance mechanism through induction of T cell recruitment and activation of IL-13/IL-33-mediated pathway." (PMID 32754302, 2020). "Aberrant expression of PCAT-1 in the tumor microenvironment negative regulates p27/CDK6 by inducing G0/G1 cell cycle arrest and AMPK augmentation, contributing to a tumor-favoring metabolic status." (PMID 32754302, 2020). "Subsequent PCAT-1 knockdown impaired CAF-mediated stromal activation, and reversed chemoresistance and tumor growth in vivo." (PMID 32754302, 2020). "In a recent study, the expression values of PCAT1 in paired HNSCC tissues and adjacent non-tumor tissues were measured using qRT-PCR." (PMID 32024523, 2020). "To explore the potential of targeting lncRNA PCAT1 in CRPC, we employed lentiviral injection into CRPC tumor xenografts." (PMID 30773595, 2019). "The expression of PCAT-1 was measured by quantitative real-time PCR in 23 paired human HNSCC tissues and adjacent non-tumor tissue specimens." (PMID 30987615, 2019). "Notably, in contrast to RhOME2, RhOME1 (PCAT1) and RhOME3 (CCDC26) were previously identified as MYC regulatory regions in other tumor entities." (PMID 38040699, 2023). "Moreover, we checked the PCAT1 and SOX2 expression in the tumour tissues, and the quantitative real‐time polymerase chain reaction (qRT‐PCR) results suggested that PCAT1 depletion downregulated SOX2 in vivo as well." (PMID 35415876, 2022). "Rather, PCAT-1 knockdown impaired CAF-mediated stromal activation and tumor growth in vivo." (PMID 35087824, 2021). "PCAT1 and MIR155HG could even serve as predictive biomarkers for probable survival time and metastatic potential in CRC patients after tumour resection." (PMID 30205577, 2018). "Further evidence of this hypothesis is seen in tumours with PCAT1 fusions, where tumours with this fusion had shorter tumour TL than samples without it44." (PMID 34824250, 2021). "Likewise, the relative highest levels of PCAT-1 were detected in chemoresistant patients in advanced stage rather than in chemonaive-responding to chemotherapy regimen- early stage individuals, indicating the critical role of PCAT-1 in tumor propagation." (PMID 32754302, 2020).
tumor (continued). "We examined PCAT-1 expression in archived HNSCC patient samples and observed a significant increase in PCAT-1 expression in HNSCC tumor samples (n = 23) compared to the adjacent non-tumor tissue." (PMID 30987615, 2019).
intestinal diseases (1 paper, 2024). "This led us to hypothesize that PCAT1 could differentiate CRC from non-malignant intestinal diseases." (PMID 39640681, 2024).
prostate (1 paper, 2020). "For example, the DE-lncRNAs PVT1, PCAT1, and PCAT10/CTBP1-AS have been previously studied and implicated in prostate tumorigenesis." (PMID 32059012, 2020).
PCAT1 also shares sentences with these, for which no sentence is quoted: cholangiocarcinoma (2 papers); lymph node metastasis (2); bipolar disorder (1); bladder tumor (1); brain cancer (1); brain tumors (1); diffuse large B-cell lymphoma (1); gastric adenocarcinoma (1); glioma (1); head and neck cancer (1); lung adenocarcinoma (1); melanoma (1); mesothelioma (1); multinodular goiter (1); nasopharyngeal carcinoma (1); oral cavity cancer (1); osteoporosis (1); pancreatic cancer (1); papillary thyroid carcinoma (1); periodontitis (1).